AKAP9 (A-kinase anchoring protein 9)
Diseases named in the same sentence as AKAP9 in open-access papers (continued):
Sharing a sentence is not in itself a finding about the gene and the disease.
tumor (18 papers, 2010 to 2026). "Among the 95 primary tumor samples, AKAP9, KDM2B, MAGED1, MKI67, PCLO, and TRAF1 mutations were identified as single-occurrence events and were absent in the metastatic samples." (PMID 41614915, 2026). "Among the primary tumor samples, AKAP9, KDM2B, MAGED1, MKI67, PCLO, and TRAF1 mutations were identified." (PMID 41614915, 2026). "In vitro studies of molecular events associated with AKAP9 gene expression alteration in tumour cells linked it to the action of proteins such as CDH1, Cdc42 interacting protein 4, and the Wnt/β-Catenin signalling pathway." (PMID 38203733, 2024). "The mutation frequencies of Akap9, Cdh11, and Muc4 are less than 7% in the TCGA tumor database, whereas their mutation rates are higher than 85% in the murine OSCC cell lines analyzed." (PMID 33302499, 2020). "The unique mutation spectrum present in tumor cells and the down-regulation of Akap9 in tumors needs further study." (PMID 33302499, 2020). "Moreover, primary tumor samples had exclusive mutations in AKAP9, KDM2B, MAGED1, MKI67, PCLO, and TRAF1." (PMID 41614915, 2026). "Increased AKAP9 expression was revealed to correlate with older age and more advanced tumours (pT2-4 vs. pT1 and stage II-IV vs. I)." (PMID 38203733, 2024). "AKAP9 expression was also increased in older age patients (over median age equal 50 years) and in samples obtained from the more advanced tumour (characterised by pT3 and pT4 parameters)." (PMID 38203733, 2024). "During the tumor formation period, we found that tumor derived from AKAP9 expressing cells grew significantly faster than tumors derived from EV expressing cells." (PMID 36317124, 2022). "Elevated A-kinase anchor protein 9 (AKAP9) expression has previously been found to enhance tumour growth and metastasis in vivo." (PMID 35583632, 2022). "At the end of this assay (31 days), the tumor size and weight were much higher in AKAP9 expressing group than EV expressing group." (PMID 36317124, 2022). "There was a significant increase in the expression of AKAP9 in tumor tissues compared to the control tissue samples." (PMID 34679534, 2021). "Indeed, AKAP9 level is correlated with the depth of tumor infiltration and metastasis." (PMID 34679534, 2021). "Similarly, an AKAP9 mutation was detected in circulating tumor DNA upon relapse, but not in the primary tumor or in blood samples prior disease progression." (PMID 29433456, 2018). "The AKAP9 p.H562Q missense mutation was not seen in the primary tumor and might have been missed due to tumor cell heterogeneity." (PMID 27270325, 2016). "To investigate the effects of AKAP9 on tumor growth in vivo, we performed xenograft mouse assay by subcutaneously injecting the SNU-1 cells that express EV or AKAP9 into nude mice." (PMID 36317124, 2022). "Seven proteins (MYL6, AKAP9, ALDR, HS71A, KHDR1, ROA3, TAGL2) were part of both the BMI1 and RYBP chromatome, four of which (AKAP9, MYL6, ALDR and TAGL2) were identified as upregulated in IDH-wild type GBM samples versus non-tumour using TCGA datasets." (PMID 34316702, 2021). "Based on our observation of increased expression of the AKAP9 gene in more advanced tumours, it can be assumed that this is not an early event of the carcinogenesis process." (PMID 38203733, 2024). "Moreover, AKAP9 is overexpressed in CRC patients and promotes CRC and tumor metastasis." (PMID 36317124, 2022).
neurological disease (2 papers, 2015 to 2022). "AKAP9 deficiency and associated defects in T cell activation in tissues were associated with a reduction of disease in EAE as determined by neurological disease scoring and histological evaluation." (PMID 26680259, 2015).
AKAP9 also shares sentences with these, for which no sentence is quoted: lung carcinoma (4 papers); Brugada syndrome (2); cardiac diseases (2); viral infection (2); Anxiety (1); Arrhythmia (1); cardiac arrest (1); cardiac hypertrophy (1); colon cancer (1); cyst (1); diffuse large B-cell lymphoma (1); follicular thyroid cancer (1); Geleophysic dysplasia 1 (1); glomerulonephritis (1); hearing loss (1); hereditary cardiomyopathies (1); immune system disorder (1); ischaemia (1); kidney cancer (1); kidney disease (1); leukaemia (1); metastatic melanoma (1); metastatic tumors (1); mild cognitive impairment (1); ovarian carcinoma (1); pancreatic cancer (1); papillary thyroid cancer (1); polymorphic ventricular tachycardia (1); renal carcinoma (1); sickle-cell anemia (1).
A further 4 diseases each share a sentence with AKAP9 in 1 paper.